NEK2 (NIMA related kinase 2)
Diseases named in the same sentence as NEK2 in open-access papers (continued):
Sharing a sentence is not in itself a finding about the gene and the disease.
tumor (continued). "Overall, these data demonstrate that NEK2 inhibition via JH295 treatment significantly prolongs survival and reduces tumor burden in PEL-bearing mice." (PMID 38592451, 2024). "In summary, our experiments identify NEK2 as a downstream target of YAP-MMB that is required for proliferation, transformation and survival of YAP-dependent tumor cells." (PMID 38182898, 2024). "We also demonstrate that treatment of PEL-bearing mice with the NEK2 inhibitor, JH295, significantly reduces tumor burden and prolongs survival compared with control mice, with no harmful effects on liver health." (PMID 38592451, 2024). "In present study, we first showed that NEK2 was highly expressed in ESCC and can promote the tumor cells metastasis by EMT." (PMID 37233832, 2023). "High levels of NEK2 and JMJD4 were both related to tumor recurrence, and shorter RFS and OS rates (P<0.001)." (PMID 37600577, 2023). "These candidates included five upregulated genes—NUF2, KIF4A, KIF18B, NEK2, and DLGAP5—and one downregulated gene—LRRK2—in the tumor tissues of TCGA databases." (PMID 36499051, 2022). "Consistently, NUF2, KIF4A, KIF18B, DLGAP5, and NEK2 were highly overexpressed, whereas LRRK2 was significantly downregulated in the tumor tissues of all datasets." (PMID 36499051, 2022). "Our group and others have suggested that Nek2 maintains high levels of CA/CIN, tumor growth, and drug resistance." (PMID 33907253, 2021). "We found that four of the hub genes (TOP2A, AURKA, NEK2, and RACGAP1) can serve as tumor therapeutic targets for drugs approved by FDA." (PMID 33946043, 2021). "In light of this, we additionally administrated NEK2 inhibitor and/or anti-PD-L1 antibody to KPC-bearing mice, after which both tumor volumes and tumor weight decreased significantly in mice that received the combined treatment." (PMID 34315872, 2021). "Collectively, these observations strongly suggest that elevated NEK2 levels in TNBC cells support a pro-mesenchymal splicing program by controlling RBFOX2 expression, thus enhancing tumor aggressiveness and invasiveness." (PMID 34930366, 2021). "From 370, 445, and 455 different tumor studies, TTK, NEK2, and CDK1 gene expression data were collected." (PMID 34072728, 2021). "Elevated NEK2 and PIM1 expression were related to aggressive tumor phenotype and indirectly affected the overall survival of BP-NEN patients." (PMID 32504181, 2020). "However, study has shown that the mRNA expression of NEK2 in HCC tissues was lower than adjacent normal tissues, and was associated with larger tumor diameter, higher alpha-fetoprotein (AFP) concentration, higher tumor stage, worse prognosis and shorter survival time." (PMID 33109182, 2020). "NEK2 was proved to be overexpressed in PDAC tissues and significantly related to histological differentiation, lymph node metastasis, and tumor stage." (PMID 32537471, 2020). "MGI is a gene expression assay, measuring the expression of five genes (BUB1B, CENPA, NEK2, RACGAP1, RRM2) related to histological grade and tumor progression, which recapitulates tumor grade and can predict the clinical outcome with high performance." (PMID 33287297, 2020). "To further validate the dysregulation of Nek2, we detected its expression in 102 paraffin-embedded HCC tissues and paired non-tumor tissues by immunohistochemistry." (PMID 31319849, 2019). "Our study proves that Nek2 induces HCC sorafenib resistance via β-catenin and suggests a novel therapeutic strategy to improve the anti-tumor effects of sorafenib in HCC." (PMID 31319849, 2019). "NEK2, DLGAP5 and ECT2 expression levels were significantly elevated in tumor tissues compared with normal lung tissues." (PMID 28808310, 2017). "To investigate the biological significance of NEK2 in HCC, we injected SMCC-7721-shNEK2 and Huh7-NEK2 cells with their corresponding controls subcutaneously into nude mice and monitored the tumor growth." (PMID 28881785, 2017).
tumor (continued). "The data identified several kinases that are up-regulated in tumor cells, including; MET, PFTK1, BUB1, CKS1B, EIF2AK2, and NEK2." (PMID 22280838, 2012). "Additionally, we found that NEK2-targeting shRNA and TAI-1 treatments inhibited the ectopic tumor cell growth in Rb cell line and ROs." (PMID 41535675, 2026). "Moreover, we found that NEK2 and NUF2 were overexpressed in GBC tumor tissues and validated their function in the pro-proliferation of GBC cells." (PMID 40220284, 2025). "Additionally, NEK2 inactivates the Hippo pathway by dephosphorylating MST1/2, further increasing YAP levels and contributing to tumor progression." (PMID 41256331, 2025). "While deletions were included in this analysis, they occurred in <1% of tumors, and there were no tumor samples with a NEK2 deletion." (PMID 39826695, 2025). "NEK2 inhibition resulted in PEL apoptosis and reduced tumor burden in a mouse model." (PMID 38592451, 2024). "The outcomes demonstrated that NEK2 gene expression was higher in KIRC tumor tissues (T) than in non-tumor tissues (N)." (PMID 38758909, 2024). "Interestingly, through double immunofluorescence staining of NEK2 and CD8 on ccRCC tissue slices, we found mean fluorescence intensity (MFI) of CD8 (green) significantly increased with the growth of tumor stage, along with the increasing MFI of NEK2 (red)." (PMID 38758909, 2024). "Additionally, according to the UALCAN database, the mRNA expression levels of NEK2, NEK3, NEK4, NEK5, NEK6, and NEK8 were significantly positively correlated with the tumour grade, whereas that of NEK10 was inversely associated with this factor." (PMID 38706902, 2024). "Altered expression levels of never in mitosis gene-A-related kinase 2 (NEK2) can impact drug resistance and tumor progression." (PMID 39562162, 2024). "Notably, a recent study showed that knockout of NEK2 expression suppressed breast lung cancer cells migration and invasion by mutant EGFR, thereby exerting anti-tumor effect." (PMID 37233832, 2023). "Interestingly, the expression levels of NEK2, NEK6, and NEK10 were not only remarkably correlated with the tumor stage but also with the molecular subtype." (PMID 35368696, 2022). "In particular, stratification of BC patients for receptors status revealed that NEK2 is expressed at higher levels in ER- and PR-negative tumours, while no significant changes were observed when patients were stratified for HER2 amplification." (PMID 34930366, 2021). "Additionally, the TOP2A, RRM2, NEK2, CDK1, and CCNB1 proteins were overexpressed in tumor liver tissues as compared to normal liver tissues according to the Human Protein Atlas database and previous studies." (PMID 34681056, 2021). "In recent years, several studies have shown that NEK2 is overexpressed in CRC, and may affect tumor progression and patient prognosis through various pathways." (PMID 33190424, 2021). "More importantly, the significantly negative prognostic relevance of NEK2 was observed in a tumor tissue microarray." (PMID 34315872, 2021). "We found that knockdown of Beclin‐1 did not inhibit tumor growth, but significantly sensitized NEK2‐OE KMS11 MM cells to BTZ." (PMID 31955515, 2020). "Among pathways and gene signatures differentially expressed between our tumor and adjacent normal samples (FDR q ≤ 1e-4), the CIN70 gene signature was enriched with genes positively correlated with Signature 17 activities (e.g., TPX2, NEK2, and KIF4A)." (PMID 33257699, 2020). "The NEK2, NDC80 and CEP250 mRNA expressions were different in relation to age, weight, recurrence status, histological grade, family HCC history, pathologic stage, tumor size, and survival time." (PMID 33109182, 2020).
tumor (continued). "On the contrary, oe circ-FBXW7 down-regulated the mRNA and protein levels of NEK2 and mTOR, and enhanced PTEN expression in the two tumor models, which further confirmed that si circ-FBXW7 promoted CRC progression through upregulation of NEK2 and mTOR, and downregulation of PTEN." (PMID 31519156, 2019). "Finally, western blotting and immunohistochemistry were used to evaluate the expression level of Nek2 in paired HCC and non-tumor tissues." (PMID 31319849, 2019). "Furthermore, high NEK2 levels in the HCC cells corresponded to greater tumor growth rate and tumor weight." (PMID 28881785, 2017). "NEK2, DLGAP5 and ECT2 were found to be highly expressed in tumor samples." (PMID 28808310, 2017). "Furthermore, SW480-derived microvesicles are enriched with CENPE, KIF15, CEP55, CCNA2, NEK2, PBK, and CDK8 that are M-phase-related transcripts involved in tumorigenesis and tumor progression." (PMID 19930720, 2009). "A relentless pursuit of developing a clinical candidate for destabilizing the Hec1/Nek2 axis has led to the discovery of TAI-95 (Entry 20), a highly effective compound, when administered orally and/or intravenously, in suppressing tumor in mice bearing human MDA-MB-231, BT474, and MCF7 xenografts." (PMID 35056661, 2022). "Interestingly, they did not observe the same phenotype which indicated that the inhibition of cellular Nek2, and not Cdk2, by viridin analogs restricted the premature centrosome separation in the human tumor cell line." (PMID 35056661, 2022). "For instance, there is evidence demonstrating that the overexpression of never in mitosis (NIMA) related kinase 2 (NEK2), a member of the NIMA-related serine/threonine kinase family and a key component of centrosome, could cause CIN in tumor cells." (PMID 30578380, 2019). "However, overexpression of Nek2, which is not expected to cause CIN, cooperates with oncogenic pathways to drive neoplastic tumour formation without apparent effects on CIN." (PMID 29693007, 2018). "Interestingly, we found that the overexpression of Nek2 does not induce spontaneous tumor formation within the transgenic mice up to 24 months after induction." (PMID 25485281, 2014). "Most of the significantly up-regulated genes were involved in cell cycle/mitosis/cell division (e.g., TTK, CENPF, NEK2), while many of those down-regulated were involved in cell adhesion/cell cycle arrest (e.g., ADRB2, APLP2, MACF1), consistent with a role of these genes in neoplasia development." (PMID 18297132, 2008). "Most importantly, we found that the combination of NEK2 and CDK4/6 inhibition decreases tumor volume in vivo in three different models without inducing overt toxicity as indicated by stable mouse weights." (PMID 39826695, 2025). "Using a PEL xenograft mouse model, we found that NEK2 inhibition significantly prolongs host survival and decreases PEL burden as measured by ascites volume, tumor weight, and in vivo imaging, with no detectable liver toxicity." (PMID 38592451, 2024). "Data from both the TCGA cohort and HCC patient samples confirmed that Nek2 is up-regulated in HCC samples, as compared to levels in non-tumor samples, and that higher expression is related to lower overall and recurrence-free survival." (PMID 31319849, 2019). "Overexpression of Nek2 (full length of Nek2 cDNA was subcloned into pMONO-Hygro-GFP vector), did not change the growth rates or average tumor mass of HCC1954/shE2F3 cells." (PMID 26512919, 2015).
infection (3 papers, 2008 to 2024). The state of being infected such as from the introduction of a foreign agent such as serum, vaccine, antigenic substance or organism. "The knock-down of the four kinases p38alpha, PKN1, NEK2 and PBK evoked apoptosis as determined via caspase 3 activation compared to the control infection (p < 0.005)." (PMID 18816379, 2008).
gastrointestinal tumors (1 paper, 2023). "NEK2 overexpression has been found in various human malignancies, including gastrointestinal tumors." (PMID 37835513, 2023).
NEK2 also shares sentences with these, for which no sentence is quoted: cholangiocarcinoma (6 papers); leukemia (3); retinitis pigmentosa (3); Usher syndrome (3); bladder carcinoma (2); endometrial cancer (2); head and neck squamous cell carcinoma (2); mantle cell lymphoma (2); testicular seminoma (2); basal cell carcinoma (1); benign breast tumors (1); brain tumor (1); carcinoids (1); Carney complex (1); congenital stationary night blindness (1); fibrosarcoma (1); follicular lymphoma (1); hearing loss (1); Infertility (1); kidney disorder (1); large cell neuroendocrine carcinoma (1); liposarcoma (1); liver disease (1); macular degeneration (1); malaria (1); malignant peripheral nerve sheath tumor (1); mesothelioma (1); monoclonal gammopathy of undetermined significance (1); MOPD type II (1); optic atrophy (1).
A further 16 diseases each share a sentence with NEK2 in 1 paper.